MDM4 (MDM4 regulator of p53)
Diseases named in the same sentence as MDM4 in open-access papers (continued):
Sharing a sentence is not in itself a finding about the gene and the disease.
colon carcinoma (16 papers, 2012 to 2024). "In our study, bioinformatics analysis and immunohistochemistry of clinical samples revealed that MDM4 expression was markedly elevated in colon cancer tissues compared to adjacent normal tissues." (PMID 39543140, 2024). "Our analysis of MDM4 gene expression changes in colon cancer tissues from the TCGA database, and its relationship with patient survival, revealed that MDM4 expression was significantly upregulated in colon cancer tissues compared to adjacent normal tissues." (PMID 39543140, 2024). "DDX58, XAF1, OAS1, IFI27, IFI44 or IFIT3 was indeed downregulated and CHST4 or TNFSF18 was upregulated in MDM4 overexpressed colon cancer cells." (PMID 38281029, 2024). "The colon cancer cell line, SW480 cells, were transiently transfected with plasmids encoding MDM4 protein." (PMID 38281029, 2024). "The results showed that overexpression of MDM4 promoted the proliferation of colon cancer cells and enhanced their resistance to the ferroptosis inducer RSL3." (PMID 39543140, 2024). "We also conducted transcriptomic sequencing to investigate the effect of MDM4 on transcript levels in colon cancer and performed qPCR to verify this." (PMID 38281029, 2024). "To comprehensively assess the impact of MDM4 inhibition in colon cancer, we established in vivo xenograft models using MDM4-overexpressing HT29 cells in BALB/c nude mice." (PMID 39543140, 2024). "The biological effect of MDM4 on tumor is controversial, its role and molecular mechanism in colon cancer progression and prognosis are still unclear." (PMID 39543140, 2024). "This study is, to our knowledge, the first population‐based case–control study assessing the impact of MDM4 SNP34091 on cancer risk in lung‐ and colon cancer." (PMID 26471763, 2015). "They include the action of miR-183 on βTrCP1 mRNA in colorectal cancer cells, the action of miR-143 on mouse pleiotrophin mRNA and the action of miR-34a on MDM4 mRNA in colon carcinoma cells." (PMID 24586143, 2014). "Immunohistochemical analysis of tissue microarrays containing 48 pairs of human colon cancer and adjacent normal tissues confirmed that MDM4 expression was significantly higher in colon cancer tissues, with immunohistochemical scores showing statistical significance (P = 0.0003)." (PMID 39543140, 2024).
colon carcinoma (continued). "These experimental results indicate that MDM4 can regulate ferroptosis in colon cancer cells." (PMID 39543140, 2024). "Furthermore, MDM4 knockdown attenuated the resistance of colon cancer cells to cisplatin, and Fer-1 was able to restore the cells’ resistance to cisplatin." (PMID 39543140, 2024). "Thereby, MDM4 enhances the stability of GPX4 protein, inhibiting ferroptosis, increasing the resistance of colon cancer patients to chemotherapy, and promoting colon cancer progression." (PMID 39543140, 2024). "The small-molecule inhibitor of MDM4, NSC146109, exhibits the tumor-suppressive activity in multiple cancer cell lines such as breast, kidney, lung and colon cancer." (PMID 38281029, 2024). "In our study, MDM4 is found to upregulate the TRIM21 expression level to inhibit the ubiquitination of GPX4, and promotes colon cancer progression." (PMID 39543140, 2024).
colorectal cancer (16 papers, 2014 to 2025). A primary or metastatic malignant neoplasm that affects the colon or rectum.
acute myeloid leukemia (14 papers, 2012 to 2024). Acute myeloid leukemia (AML) is a group of neoplasms arising from precursor cells committed to the myeloid cell-line differentiation. "MDM4 has been implicated as a common mechanism for the transition from preleukemia to acute myeloid leukemia in several genetic disease subtypes." (PMID 38578040, 2024). "Second, high expression of miR-10a in acute myeloid leukemia has been shown to associate strongly with negative regulation of MDM4, and to repress an MDM4 3′ UTR reporter." (PMID 22870278, 2012). "A second miR to target the classic MDM4 3′-UTR region is miR-10a and its high expression levels are linked to acute myeloid leukemia." (PMID 30689920, 2019). "An example of its pre-clinical success is in acute myeloid leukemia models (AML), where MDM4-FL is overexpressed." (PMID 30689920, 2019).
leukemia (8 papers, 2009 to 2022). A malignant (clonal) hematologic disorder, involving hematopoietic stem cells and characterized by the presence of primitive or atypical myeloid or lymphoid cells in the bone marrow and the blood. "This MDM4-degrader activity of MMRi62 was found to be associated with potent apoptosis induction in leukemia cells." (PMID 35992795, 2022). "Eliminating MDM4 and MDM2 by MMRi62 hits the key drug targets in AML because MDM4 is a pervasive driver of leukemogenesis in multiple mouse leukemia models, and MDM2 overexpression induced by MTF2 loss is a mediator for refractory AML." (PMID 35992795, 2022). "Here, we describe the identification and characterization of MMRi62 as an MDM4-degrader and apoptosis inducer in leukemia cells." (PMID 35992795, 2022). "Whether MDM4 is the major determinant of MMRi62 sensitivity in leukemia cells could not be determined because of technical difficulties in obtaining shMDM4 leukemia cells." (PMID 35992795, 2022). "In fact, Mdm4 has been reported to be amplified in a panel of leukemia cell lines." (PMID 24659749, 2014). "However, whether MMRi62 selectively kills MDM2-high or MDM4-high leukemia cells needs to be verified in the future." (PMID 35992795, 2022). "As expected, MMRi62 increased ubiquitinated species of MDM2B and MDM4 (smearing ladders of protein bands above MDM2B or MDM4 bands), which is consistent with the result that only MMRi62 induced proteasomal degradation of MDM4 and MDM2 proteins in leukemia cells." (PMID 35992795, 2022).
liver cancer (8 papers, 2019 to 2025). An epithelial or non-epithelial malignant neoplasm that arises from the liver. "Additionally, splice variants of MDM4 may influence its function and stability, affecting the biological behavior of liver cancer cells." (PMID 40226576, 2025). "To confirm the regulatory role of the circ_0001175/miR‐130a‐5p/MDM4 axis in NS3‐mediated liver cancer progression, we established a xenograft model." (PMID 40226576, 2025). "Among these, MDM4 exhibited the highest expression in NS3‐transfected liver cancer cells, as confirmed by RT‐qPCR." (PMID 40226576, 2025). "For instance, a study conducted in eastern China reported that the GG variant of the rs1380576 locus in the MDM4 gene is associated with a reduced risk of liver cancer, particularly in elderly males, nonsmokers, and nondrinkers." (PMID 40226576, 2025). "Additionally, HCV‐positive liver cancer patients showed significantly elevated MDM4 mRNA levels compared to HCV‐negative patients." (PMID 40226576, 2025).
non-small cell lung carcinoma (8 papers, 2012 to 2025). A group of at least three distinct histological types of lung cancer, including non-small cell squamous cell carcinoma, adenocarcinoma, and large cell carcinoma. "Additionally, the MDM4 rs4245739 AC genotype may be associated with increased overall survival in non-small cell lung cancer, when compared to the AA genotype." (PMID 27687591, 2016). "Correlation between cisplatin resistance and elevated MDM4 expression levels, in non-small cell lung cancer, also predicts the scope for combined MDM4 inhibition in this disease." (PMID 30689920, 2019). "While other studies have also noted MDM2/MDM4 alterations in select HPD patients, this is not the case in non-small cell lung carcinoma (NSCLC)." (PMID 31340855, 2019).
osteosarcoma (8 papers, 2012 to 2023). A usually aggressive malignant bone-forming mesenchymal neoplasm, predominantly affecting adolescents and young adults. "As amplification of MDM4 is frequently observed in sarcomas, this study examined the therapeutic potential of XI-006 for the treatment of Ewing and osteosarcoma." (PMID 26095524, 2015). "The function of miR-199a-3p and miR-34a in cell proliferation and apoptosis, it was clearly dependent on the presence of mTOR, MET and MDM4 gene in human osteosarcoma cells." (PMID 24957404, 2014). "Cell line sensitivity to XI-006 was not correlated with MDM4 mRNA or protein levels, and reduction of MDM4 mRNA and protein levels were only observed in the least sensitive Ewing sarcoma and osteosarcoma cell lines at high XI-006 concentrations (>1 μM) that also induced DNA damage." (PMID 26095524, 2015). "Our research demonstrated that miR-199a-3p and miR-34a could down-regulate its target genes, mTOR, MET and MDM4 in human osteosarcoma cells." (PMID 24957404, 2014).